ME2 (malic enzyme 2)
Description:
NAD-dependent mitochondrial malic enzyme that catalyzes the oxidative decarboxylation of malate to pyruvate.
Synonyms: ODS1
Tractability: Small molecule: a structure with a bound ligand is known; it has a high-quality binding pocket. PROTAC: ubiquitination databases record sites on it; its protein half-life has been measured; a small molecule that binds it is known.
Target class: Enzyme; Oxidoreductase
Gene: Protein-coding gene on chromosome 18 (50,878,819 to 50,954,257, forward strand). Ensembl gene ENSG00000082212.
Subcellular location: Mitochondrion matrix
Subcellular location (Human Protein Atlas): Mitochondria
Pathways (Reactome):
Metabolism: Pyruvate metabolism
Metabolism of proteins: Mitochondrial protein degradation
Gene Ontology:
Molecular function: malate dehydrogenase (decarboxylating) (NAD+) activity; malic enzyme activity; oxaloacetate decarboxylase activity; electron transfer activity; NAD binding; oxidoreductase activity, acting on the CH-OH group of donors, NAD or NADP as acceptor
Biological process: regulation of NADP metabolic process
Cellular component: mitochondrial matrix; mitochondrion
Genetic constraint (gnomAD): Loss-of-function variants: 17 observed, 23.94 expected, observed/expected ratio (o/e) 0.71, 90% interval 0.49 to 1.07. The upper end of that interval is the gene's LOEUF score, 1.07, which puts it in group 4 of 6, group 1 being the genes least tolerant of losing a copy. Missense variants: 265 observed, 328.35 expected, observed/expected ratio (o/e) 0.81, 90% interval 0.73 to 0.89. Synonymous variants: 101 observed, 118.18 expected, observed/expected ratio (o/e) 0.85, 90% interval 0.73 to 1.01.
Homologues: Orthologues: macaque ME2 (99% identical), chimpanzee ME2 (97% identical), guinea pig ME2 (94% identical), pig ME2 (93% identical), dog ME2 (92% identical), rabbit ME2 (91% identical), mouse Me2 (89% identical), rat Me2 (89% identical), tropical clawed frog me2 (78% identical), zebrafish me2 (75% identical), Drosophila melanogaster Men-b (53% identical), Caenorhabditis elegans men-1 (50% identical), and 4 more. Paralogues in human: ME3 (54% identical), ME1 (53% identical).
Diseases named in the same sentence as ME2 in open-access papers:
ME2 is named in the same sentence as 42 diseases in open-access papers, as found by Europe PMC text mining. Sharing a sentence is not in itself a finding about the gene and the disease. The quoted sentences say what the papers report.
melanoma (8 papers, 2016 to 2023). A malignant, usually aggressive tumor composed of atypical, neoplastic melanocytes. "Although ME2 expression has been found to influence the migration and invasion of melanoma cells, this function is related to the energy supply for cell mobility." (PMID 37110198, 2023). "Multiple studies have demonstrated that ME2 plays a crucial role in the development of numerous human cancers, including melanoma and glioma." (PMID 37079187, 2023). "Malic enzyme 2 (ME2), which localizes to mitochondria, was expressed by all melanomas at similar levels." (PMID 35110412, 2022). "ME2 transcripts and protein were increased in melanomas whereas ME1 and ME3 transcripts either decreased or remained unchanged." (PMID 33808495, 2021). "ME2 knockdown in melanoma cells increases ROS levels and impairs anchorage-independent growth in vitro and tumorigenicity in vivo." (PMID 28649560, 2017). "It is noteworthy that, compared to normal melanocytes, melanoma cells exhibit increased expression of ME2 and reduced expression of NADP-dependent ME3." (PMID 28649560, 2017). "However, previous study demonstrated that ME2 knockdown reduced ATP production and increased ROS level in melanoma cells." (PMID 27166188, 2016). "Recent studies showed that malic enzyme isoform 2 (ME2) might serve as a target for the suppression of tumor growth and invasiveness in several tumor cells, including lung cancer and melanoma cells." (PMID 27166188, 2016). "Previous studies have confirmed that malic enzyme 2 (ME2), a key enzyme in the tricarboxylic acid (TCA) cycle, is abnormally expressed in some malignant tumors, including melanoma, non–small-cell lung cancer, and pancreatic cancer." (PMID 34381734, 2021). "This inconsistency may be due to differences in ROS clearance (reduced NADPH) and ROS generation (reduced ATP synthesis) when ME2 is depleted in GBM and melanoma cells, respectively." (PMID 27166188, 2016).
pancreatic cancer (8 papers, 2017 to 2025). "In pancreatic cancer, for example, malic enzyme 2 (ME2) is frequently co-deleted along with the SMAD4 tumor suppressor, rendering tumor cells dependent on the only remaining mitochondrial malic enzyme isoform, ME3." (PMID 33540663, 2021). "The function and expression of ME2 in patients with malignancies, such as pancreatic cancer, Morris hepatomas and HNSCC, have been recently reported." (PMID 32218701, 2020). "Previous work has indicated that the expression level of ME2 is noticeably increased in malignant human tissues, such as pancreatic cancer, lung cancer, head and neck squamous cell carcinoma (HNSCC), etc 15-17." (PMID 32218701, 2020). "Genomic deletion of ME2 led to a dramatic drop in NADPH levels in pancreatic cancer cell lines exposed to doxorubicin-induced oxidative stress." (PMID 28649560, 2017). "Recent studies indicated that ME2 was dysregulated in several tumors and serves as a target in the regulation of tumor proliferation, differentiation, metabolism, and invasion in various cancers, such as lung cancer, pancreatic cancer, and erythroleukemia." (PMID 34427987, 2021). "Inactivation of tumor suppressor genes such as RPS7, MRPL39, MRPS23, ME2, and NDUFB9 were diagnosed with the development of many cancer types such as colorectal cancer, gastric cancer, breast cancer, and pancreatic cancer, but loss of these genes may be responsible for the development of GBM." (PMID 31137733, 2019).
lung cancer (7 papers, 2007 to 2023). A malignant neoplasm involving the lung. "Since silencing ME2 may alter TCA cycle metabolism and cause malate accumulation and pyruvate decrease, which will change growth in lung cancer cells, we next sought to explore the underlying mechanism involved in the action of ME2 on cell proliferation and migration in HCC." (PMID 34427987, 2021). "A ME2-specific inhibitor embonic acid (EA) has been shown to inhibit lung cancer cell growth and induce cellular senescence by inhibiting ME2." (PMID 37079187, 2023). "The ELAC1 locus was targeted in a 300 kb homozygous deletion in lung cancer, which also involved the ME2 gene." (PMID 17201907, 2007). "ME2 plays a crucial role in modulating lung cancer differentiation and growth." (PMID 37110198, 2023). "Furthermore, another study clarified that ME2 depletion would inhibit lung cancer growth via inactivation of the PI3K/AKT axis." (PMID 34427987, 2021).
glioma (5 papers, 2016 to 2024). A benign or malignant brain and spinal cord tumor that arises from glial cells (astrocytes, oligodendrocytes, ependymal cells). "We found that ME2 is associated with overall survival of patients and promotes the proliferation, migration, and invasion of glioma cells." (PMID 34381734, 2021). "We performed a preliminary analysis of data obtained from Gene Expression Omnibus profiles and determined that malic enzyme 2 (ME2) expression was positively associated with WHO grade in human primary gliomas." (PMID 27166188, 2016). "The GEO database showed that WHO pathological grading of human glioma and ME2 expression were associated." (PMID 27166188, 2016). "Its expression is positively associated with WHO tumor grade in human primary gliomas, suggesting that ME2 could be a predictive biomarker in human gliomas." (PMID 38786726, 2024). "Because ME2 is essential for reactive oxygen species (ROS) homeostasis, we examined the effects of ME2 on ROS oxidation in glioma cells using a MitoProbeTM JC-1 fluorescent probe." (PMID 34381734, 2021). "A western blot assay was then used to detect the effects of ME2 expression on lipid metabolism–related proteins in glioma cells." (PMID 34381734, 2021). "In this study, we focused on the functions of ME2 in GBM cells, GBM8401 and LN229, based on the positive correlation between the expression level of ME2 and glioma grade." (PMID 27166188, 2016). "Therefore, ME2 is highly expressed in MES-phenotype glioma cells and is positively correlated with MES features in GBM." (PMID 34381734, 2021). "In addition, ME2 expression gradually increased from normal brain tissue to low-grade glioma and then to malignant glioma." (PMID 34381734, 2021). "Importantly, to our knowledge, ME2 promoted PMT of glioma cells and reprogrammed lipogenesis via the AMPK–SREBP-1–ACSS2 pathway." (PMID 34381734, 2021). "To determine whether ME2 promotes PMT of glioma cells, we performed a western blot assay to detect the expression of MES markers MET, YKL40, N-cadherin, and vimentin; epithelial marker E-cadherin; and PN marker OLIG2." (PMID 34381734, 2021). "Therefore, we suggest that ME2 enhances de novo synthesis of fatty acids mainly via the AMPK–SREBP-1–ACSS2 pathway in glioma." (PMID 34381734, 2021). "Our preliminary analysis of data from Gene Expression Omnibus (GEO) profiles revealed that ME2 expression is positively associated with WHO grade in human primary gliomas, suggesting that ME2 may be, at least, a predictive biomarker in human gliomas." (PMID 27166188, 2016). "Thus, ME2 promotes PMT of glioma cells and inhibits the production of mitochondrial ROS." (PMID 34381734, 2021). "We confirmed that ME2 promotes SREBP-1 maturation and nuclear localization and increases ACSS2 expression, indicating that ME2 upregulates de novo lipogenesis, probably via AMPK–SREBP-1–ACSS2, in glioma cells." (PMID 34381734, 2021). "In conclusion, ME2 promotes PMT of GBM cells, and ACSS2 has an important role in the ME2-induced de novo synthesis of fatty acids in glioma cells." (PMID 34381734, 2021). "Importantly, we found that ME2 was correlated with the GBM MES phenotype and promoted PMT and reprograming of the lipogenesis pathway via AMPK–SREBP-1–ACSS2 in glioma cells." (PMID 34381734, 2021). "Furthermore, we demonstrated that ME2 was positively correlated with mesenchymal features in GBM and promoted proliferation, migration, and invasion of glioma cells." (PMID 34381734, 2021). "The results showed that ME2 overexpression in SW1783 and U251MG cells upregulated the expression of N-cadherin, vimentin, YKL40, and MET expression, whereas it downregulated the expression of E-cadherin and OLIG2, suggesting that ME2 promotes PMT of glioma cells." (PMID 34381734, 2021). "Therefore, ME2 has potential as a new classification marker in GBM and could provide a new approach to glioma treatment." (PMID 34381734, 2021).
glioma (continued). "However, the potential function of ME2 has not been thoroughly investigated in human gliomas." (PMID 27166188, 2016). "The ME2 mRNA expression levels in patient tissue samples were statistically greater in grade III and grade IV gliomas than in non-tumor controls (p<0.005)." (PMID 27166188, 2016).
breast carcinoma (4 papers, 2010 to 2023). "We have found marked effects in several tumor types in vitro and in vivo: in MCF7 breast cancer cells and A549 non-small cell lung cancer cells, ME2 silencing leads to differentiation and to increased apoptosis (data not shown)." (PMID 20824065, 2010). "Moreover, the anti-cancer effect of some herbal compounds such as Eupatilin on breast cancer has not been studied, or new targeting pathways for cancer prevention have been introduced including Malic enzyme 2 and Phosphoglycerate mutase 1 that are noteworthy." (PMID 32952942, 2020).
gastric cancer (4 papers, 2019 to 2025). A primary or metastatic malignant neoplasm involving the stomach. "This study unveiled genomic factors driving tumour metabolic reprogramming, including the amplification of the malic enzyme 2 and the proposed targeting of asparaginase metabolism in gastric cancer." (PMID 40136651, 2025). "The present study showed that GATA6 knockout resulted in the down-regulation of ME2 in trastuzumab resistant gastric cancer cells, which in turn reduced ATP production and ultimately inhibited the proliferation of cells." (PMID 33173435, 2020).
hepatocellular carcinoma (4 papers, 2021 to 2026). A malignant tumor that arises from hepatocytes. "Hyperactivated mitophagy caused by malic enzyme 2 knockdown disrupts mitochondrial homeostasis, which suppresses the proliferative capacity of hepatoma cells." (PMID 41876455, 2026). "The expression of ME2-R67K was strongly associated with a poor prognosis for individuals with hepatocellular carcinoma according to survival analysis." (PMID 39528487, 2024). "In the present study, we demonstrate the important role of ME2 methylation in hepatocellular carcinoma." (PMID 39528487, 2024). "In the previous experiments we observed that in hepatocellular carcinoma, ME2 interacts with PRMT1 and plays a role in the growth and invasive metastasis of HCC cells." (PMID 39528487, 2024). "We knocked down the expression of ME2 by using two different sets of small interfering RNA (siRNA) in human hepatocellular carcinoma SK-Hep 1 cells." (PMID 37110198, 2023). "Consistent with the results in SK-Hep 1 cells, ME2-depletion also inhibited cell migration in human hepatocellular carcinoma Huh 7 cells, whereas up-regulation of ME2 enhanced it." (PMID 37110198, 2023). "In this study, we show the role of ME2 in promoting the migration and invasion of hepatocellular carcinoma cells." (PMID 37110198, 2023). "However, little is known about the functional regulatory mechanisms of ME2 in hepatocellular carcinoma." (PMID 39528487, 2024). "In this work, we show that human hepatocellular carcinoma (HCC) tissues contain high levels of ME2 and that the methylation of ME2 stimulates the growth and migration of HCC cells." (PMID 39528487, 2024). "Next, we investigated whether the regulation of ME2 by PRMT1 contributes to hepatocellular cancer." (PMID 39528487, 2024). "In hepatocellular carcinoma cells treated with a PRMT1 inhibitor (AMI-1), the protein expression level of ME2 was significantly downregulated after 72 h of treatment." (PMID 39528487, 2024). "Moreover, according to the clinical correlation between tumor tissues and adjacent normal tissues of 73 HCC patients, PRMT1 was highly expressed in HCC and was positively correlated with ME2 methylation and poor clinical prognosis in hepatocellular carcinoma patients." (PMID 39528487, 2024).
epilepsy (3 papers, 2011 to 2023). A brain disorder characterized by episodes of abnormally increased neuronal discharge resulting in transient episodes of sensory or motor neurological dysfunction, or psychic dysfunction. "The results of our analysis identified a promising epilepsy candidate gene for follow-up sequencing: malic enzyme 2 (ME2; min p < 0.0084)." (PMID 28536599, 2017). "Human mitochondrial NAD(P)+-dependent malic enzyme (ME2) is well-known for its role in cell metabolism, which may be involved in cancer or epilepsy." (PMID 37217557, 2023). "This breed had the lowest overall average heterozygosity and results for eleven genes, three of which are human epilepsy-associated (GABRD, KCNA1, and ME2), could not be determined due to low heterozygosity." (PMID 21518446, 2011).
pancreatic ductal adenocarcinoma (3 papers, 2021 to 2024). An infiltrating adenocarcinoma that arises from the epithelial cells of the pancreas. "Genetic deletion of SMAD4 that occurs in almost 30% of pancreatic ductal adenocarcinoma (PDAC) often associates simultaneous deletion of malic enzyme 2 (ME2) gene, as these genes locate within 200 kb distance in the same chromosome." (PMID 34359636, 2021). "Interestingly, loss of ME2 in pancreatic ductal adenocarcinoma (PDAC) has been shown to require ME3 for metabolic compensation and survival." (PMID 38263319, 2024).
acute myeloid leukemia (2 papers, 2019 to 2023). Acute myeloid leukemia (AML) is a group of neoplasms arising from precursor cells committed to the myeloid cell-line differentiation. "KDM3B is a H3K9me1/me2-specific demethylase that was initially suspected of inhibiting the tumor activity of hematopoietic malignancies due to its location in the 5q31 chromosome region, which is a frequently deleted region in myelodysplastic syndromes (MDS) and acute myeloid leukemia (AML)." (PMID 31592194, 2019).
generalized epilepsy (2 papers, 2021 to 2022). Epilepsy that is characterized by generalized seizure types and may have typical interictal and/or ictal EEG findings that accompany generalized seizure types (for example generalized spike-wave). "In humans, recessive ME2 mutations predispose to idiopathic generalized epilepsy because genetic variation of the ME2 gene confers susceptibility to idiopathic generalized epilepsy." (PMID 34884868, 2021). "ME2 has been shown to be associated with generalized epilepsy, suggesting that ME2 may affect both the nervous system and muscle strength." (PMID 36520780, 2022).
leukemia (2 papers, 2010 to 2023). A malignant (clonal) hematologic disorder, involving hematopoietic stem cells and characterized by the presence of primitive or atypical myeloid or lymphoid cells in the bone marrow and the blood. "Collectively our data point to ME2 as a potentially novel metabolic target for leukemia therapy." (PMID 20824065, 2010). "AOA induced leukemia cell death (mainly apoptotic) when ME2 was silenced (bottom)." (PMID 20824065, 2010). "Though no differentiation was observed in AOA treated leukemia cells, the response of ME2 knockdown and control cells to AOA treatment was quite dramatic." (PMID 20824065, 2010). "5.0 mM NAC completely inhibited endogenous ROS in ME2 knockdown leukemia cells, without affecting differentiation, suggesting that ROS production is only a by-product of ME2 knockdown." (PMID 20824065, 2010).
ovarian carcinoma (2 papers, 2025 to 2026). A malignant neoplasm originating from the surface ovarian epithelium. "Here, it is shown that malate enzyme 2 (ME2), which metabolizes glutamine-derived malate to pyruvate, contributes to lactate production and chemotherapy resistance in ovarian cancer." (PMID 39951294, 2025).
acute lymphoblastic leukemia (1 paper, 2010). Leukemia with an acute onset, characterized by the presence of lymphoblasts in the bone marrow and the peripheral blood. "Another study suggests that ME2 may play an important role in acute lymphoblastic leukemia." (PMID 20824065, 2010).
depression (1 paper, 2022). "In addition, ME2 has been found to be associated with susceptibility to psychosis and mania, and the knockdown of ME2 may affect PI3K/AKT signaling, all suggesting that ME2 is also associated with depression." (PMID 36520780, 2022).
diabetic retinopathy (1 paper, 2017). "As a vital epigenetic modification, alteration of histone methylation is clearly associated with the development diabetic retinopathy in rodents, and H4K20me1/me2-associated DNA damage pathway might be the therapeutic targets for this ocular disease." (PMID 28338045, 2017).
dysplasia (1 paper, 2020). A usually neoplastic transformation of the cell, associated with altered architectural tissue patterns. "Indeed, a high expression level of ME2 was observed in human primary OSCC tissue (n = 176) compared with normal oral mucosal tissue (n = 42, P < 0.05), whereas the difference in the expression level of ME2 between the OSCC and dysplasia tissues was not significant (n = 69, P > 0.05)." (PMID 32218701, 2020).